PCDH20 (protocadherin 20)
Description:
Potential calcium-dependent cell-adhesion protein.
Synonyms: PCDH13; FLJ22218
Tractability: Antibody: UniProt places it where antibodies can reach, with medium confidence; UniProt predicts a signal peptide or a membrane-spanning region; its Gene Ontology location is reachable by antibodies, with medium confidence.
Gene: Protein-coding gene on chromosome 13 (61,409,685 to 61,415,849, reverse strand). Ensembl gene ENSG00000280165.
Subcellular location: Cell membrane
Subcellular location (Human Protein Atlas): Vesicles; Cytokinetic bridge
Gene Ontology:
Molecular function: RNA binding; cell adhesion molecule binding; calcium ion binding
Biological process: cell adhesion; homophilic cell-cell adhesion
Cellular component: plasma membrane; membrane
Genetic constraint (gnomAD): Loss-of-function variants: 18 observed, 38.48 expected, observed/expected ratio (o/e) 0.47, 90% interval 0.32 to 0.69. The upper end of that interval is the gene's LOEUF score, 0.69, which puts it in group 2 of 6, group 1 being the genes least tolerant of losing a copy. Missense variants: 1,161 observed, 1,217.4 expected, observed/expected ratio (o/e) 0.95, 90% interval 0.91 to 1. Synonymous variants: 495 observed, 473.59 expected, observed/expected ratio (o/e) 1.05, 90% interval 0.97 to 1.13.
Homologues: Orthologues: chimpanzee PCDH20 (99% identical), macaque PCDH20 (98% identical), rabbit PCDH20 (94% identical), pig PCDH20 (93% identical), mouse Pcdh20 (93% identical), rat Pcdh20 (92% identical), guinea pig PCDH20 (91% identical), dog PCDH20 (91% identical), tropical clawed frog pcdh20 (68% identical), zebrafish pcdh20 (53% identical). Paralogues in human: PCDH9 (33% identical), PCDH11X (33% identical), PCDH11Y (31% identical), PCDH1 (29% identical), PCDH7 (29% identical), CDH23 (23% identical), DCHS2 (23% identical), DCHS1 (21% identical), CDHR2 (21% identical), CDH1 (18% identical), CDHR1 (18% identical), CDH2 (17% identical), and 21 more.
Diseases named in the same sentence as PCDH20 in open-access papers:
PCDH20 is named in the same sentence as 26 diseases in open-access papers, as found by Europe PMC text mining. Sharing a sentence is not in itself a finding about the gene and the disease. The quoted sentences say what the papers report.
hepatocellular carcinoma (4 papers, 2016 to 2023). A malignant tumor that arises from hepatocytes. "The expression of PCDH20 is decreased or silenced in non-small cell lung cancer, hepatocellular carcinoma, and hypopharyngeal squamous cell carcinoma, but the function of PCDH20 in esophageal cancer cells is not well understood." (PMID 36248995, 2022). "In a recent study, Wnt/β-catenin signaling was inhibited by PCDH20 through phosphorylation of GSK-3β in hepatocellular carcinoma." (PMID 27351130, 2016). "PCDH20 downregulates the activation of Wnt/β-catenin signaling in hepatocellular carcinoma and hypo-pharyngeal squamous cell carcinoma, whereas the mechanism of PCDH20 inhibiting ESCC remains unknown." (PMID 36248995, 2022). "Another factor, PCDH20, was shown to serve as a tumor suppressor in ESCA, HNSC, hepatocellular carcinoma, and non-small cell lung cancer." (PMID 37958512, 2023). "Recently, protocadherin 20 has been reported as a tumor suppressor gene in hepatocellular carcinoma (HCC); however, the prognostic value of protocadherin 20 in HCC remains unclear." (PMID 27935871, 2017).
lung carcinoma (4 papers, 2014 to 2020). "Furthermore, a recent study demonstrated that promoter methylation status of another protocadherin (PCDH20) was also associated with a shorter OS in lung cancer 31; therefore, the role of other protocadherin methylation in NSCLC needs to be investigated in future studies." (PMID 26276761, 2015). "Within the same gene cluster as PCDH8 there resides PCDH17 and PCDH20 that are both hypermethylated and homozygously deleted in esophageal squamous cell carcinoma and lung cancer respectively." (PMID 24454902, 2014).
nasopharyngeal carcinoma (4 papers, 2016 to 2020). A carcinoma arising from the nasopharyngeal epithelium. "The latest studies showed reduced expressions of PCDH20 in non-small cell lung cancer, nasopharyngeal carcinoma, and HCC." (PMID 27935871, 2017). "PCDH20 expression was detected in normal lung and nasopharyngeal tissues, but was silenced or downregulated in non-small cell lung cancer and nasopharyngeal cell lines; the same was also observed in nasopharyngeal carcinoma tissues." (PMID 33369468, 2020). "PCDH20 can inhibit cell proliferation, migration and invasion by antagonizing the Wnt/β-catenin and EMT signaling pathway in nasopharyngeal cancer." (PMID 33369468, 2020).
non-small cell lung carcinoma (4 papers, 2017 to 2023). A group of at least three distinct histological types of lung cancer, including non-small cell squamous cell carcinoma, adenocarcinoma, and large cell carcinoma. "It has been reported that the frequent silencing of PCDH20 in non-small cell lung carcinoma cell lines and primary tumors was associated with promoter methylation, and that tumor cell growth was suppressed after restoration of PCDH20 expression in vitro." (PMID 27935871, 2017).
colitis (2 papers, 2023 to 2024). Inflammation of the colon. "Together, these data demonstrate that PCDH20 deficiency impairs the epithelial barrier integrity in colitis by unzipping adherens junctions via a dysregulated catenin complex." (PMID 37407995, 2023). "By administering a selective ATF6 activator, the impairment of intestinal barrier integrity and dysregulation of CHOP/β-catenin/p-p120-catenin pathway was reversed in Pcdh20-ablated mice with colitis and PCDH20-deficient colonic cell lines." (PMID 37407995, 2023). "We also showed that PCDH20 expression was negatively associated with CD severity in patients and in mice with experimental colitis." (PMID 37407995, 2023). "We found that AA147 administration reverses elevated CHOP expression, barrier defects, and colitis susceptibility in Pcdh20 CKO mice with colitis, by selectively increasing both cleaved and 90kd fragments of ATF6." (PMID 37407995, 2023). "Specifically, the loss of PCDH20 impairs intestinal barrier function by unzipping adherens junctions in mice with colitis via targeting the ATF6/CHOP/β-catenin/p120-catenin axis." (PMID 37407995, 2023). "In the setting of PCDH20 deletion, the increased proportion of enterocytes along with the loosened cell–cell adherens junctions, but not tight junctions, were the predominant causes of the barrier defect in colitis." (PMID 37407995, 2023). "Moreover, we found that PCDH20 deficiency disrupted the intestinal barrier function by suppressing the ATF6-mediatied ER stress pathway in colitis, which indicated that PCDH20 reduction played a significant role in intestinal inflammation dependent on ATF6." (PMID 37407995, 2023). "A decrease in the expression level of PCDH20 can disrupt the integrity of the intestinal mucosa, which can contribute to the development of colitis and Crohn’s disease." (PMID 38327746, 2024). "Specifically, PCDH20 helps to protect against colitis by tightening adherens junctions through the ATF6/CHOP/β-catenin/p-p120-catenin axis." (PMID 37407995, 2023). "PCDH20 mRNA and protein expression is significantly downregulated in the colonic epithelium of Crohn’s disease patients and mice with induced colitis compared with controls." (PMID 37407995, 2023). "We also detected significantly decreased intestinal permeability in AA147-treated Pcdh20 CKO colitis mice compared with those treated with PBS." (PMID 37407995, 2023). "Thus, PCDH20 deficiency could impair epithelial barrier function by downregulating ATF6 in colitis." (PMID 37407995, 2023). "Nevertheless, the expression of the CHOP/β-catenin/p-p120-catenin was partly rescued by cleaved ATF6 activated via AA147 administration in the Pcdh20 CKO mice and the PCDH20-deficient cell lines during colitis." (PMID 37407995, 2023). "Using immunohistochemistry, real-time qPCR, and immunoblot, we detected a decreased expression of PCDH20 in both colitis groups compared to that in the control groups." (PMID 37407995, 2023). "Immunoblotting further revealed that in the colitis models, β-catenin was significantly downregulated, while levels of α-catenin were slightly decreased in Pcdh20 CKO mice compared to WT mice." (PMID 37407995, 2023). "To further clarify these findings, we used TNBS to induce colitis in Pcdh20 CKO mice and observed similar results." (PMID 37407995, 2023). "Moreover, ATF6 was downregulated in the colonic epithelium of PCDH20-deficient patients with CD and Pcdh20 CKO mice with colitis." (PMID 37407995, 2023). "PCDH20 ablation impaired the intestinal barrier integrity, thus enhancing sensitivity to colitis." (PMID 37407995, 2023). "We demonstrate that PCDH20 deficiency unzips the adherens junctions between enterocytes by suppressing the ATF6/CHOP/β-catenin/p120-catenin pathway, thereby disrupting barrier integrity and enhancing sensitivity to experimental colitis." (PMID 37407995, 2023).
colitis (continued). "However, phosphosite T310 of p120-catenin was significantly downregulated, while phosphosite S288 was upregulated in Pcdh20 CKO mice with colitis when compared with WT mice with colitis, which was consistent with our phosphoproteomics analysis." (PMID 37407995, 2023). "Treatment with AA147 ameliorated DSS-induced colitis in Pcdh20 CKO mice, characterized by less weight loss, lower DAI, longer colon length, lower levels of pathological scores, and lower MPO activity in colonic tissue than those in PBS-treated Pcdh20 CKO mice with colitis." (PMID 37407995, 2023). "Nevertheless, we found the gap of adherens junctions only appeared at the late stage of colitis in Pcdh20 CKO mice, suggesting that PCDH20 regulates adherens junctions by inflammation-triggered signaling pathway." (PMID 37407995, 2023). "The expression of p120-catenin was lower in the colitis group than that in the control group, yet no statistical difference was detected between WT and Pcdh20 CKO mice with respect to colitis." (PMID 37407995, 2023). "Additionally, we found that stenosis and perforation due to PCDH20 downregulation were more common in CD patients, while stenosis and perforation were apparent in Pcdh20 CKO mice with TNBS-induced colitis." (PMID 37407995, 2023). "While stenosis and perforation were both common in Pcdh20 CKO mice with TNBS colitis, not all patients with CD progress to perforation under natural disease development." (PMID 37407995, 2023). "Therefore, to further investigate whether PCDH20 plays such a role, Pcdh20 CKO mice were subjected to DSS-induced colitis." (PMID 37407995, 2023).
Crohn disease (2 papers, 2023 to 2024). A gastrointestinal disorder characterized by chronic inflammation involving all layers of the intestinal wall, noncaseating granulomas affecting the intestinal wall and regional lymph nodes, and transmural fibrosis. "We identify the cadherin superfamily member protocadherin 20 (PCDH20) as a crucial factor in Crohn’s disease." (PMID 37407995, 2023). "Here we describe the function of PCDH20 and its mechanisms in gut homeostasis, barrier integrity, and Crohn’s disease development." (PMID 37407995, 2023).
esophageal squamous cell carcinoma (2 papers, 2014 to 2022). Esophageal squamous cell carcinoma (ESCC) is a type of esophageal carcinoma (EC) that can affect any part of the esophagus, but is usually located in the upper or middle third. "Tumor suppression is due to Wnt/β-catenin pathway antagonism and may be suppressed caused by PCDH20 downregulation through promotor methylation, whereas PCDH20 effects and regulation mechanism in esophageal squamous cell carcinoma (ESCC) remains elusive." (PMID 36248995, 2022).
liver cancer (2 papers, 2017 to 2022). An epithelial or non-epithelial malignant neoplasm that arises from the liver. "Several studies have shown that PCDH genes are also involved in liver cancer development, including PCDH10, PCDH17, PCDH19, PCDH20, PCDHGC4, and PCDHGC5." (PMID 36230503, 2022).
asthma (1 paper, 2015). "Methylated paired box 5 protein transcription factor (PAX-5a), although not being associated with asthma risk, interacted synergistically with PCDH-20." (PMID 26052354, 2015). "In an analysis of 12 genes implicated in oxidative stress pathways, higher methylation of protocadherin-20 (PCDH-20) was observed in sputa from adult smokers with asthma compared to non-asthmatic subjects with a similar smoking history and without COPD." (PMID 26052354, 2015).
colon cancer (1 paper, 2024). "Ultimately, specific methylation markers (PCDH20, APCDD1, and COCH) were identified as effective markers for identifying cluster that would benefit from immunotherapy in colon cancers." (PMID 38327746, 2024). "Furthermore, we found beneficial-cluster of specific methylation markers (PCDH20, APCDD1, COCH) that could be used in conjunction with microsatellite status to expand the pool of colon cancer patients eligible for immunotherapy." (PMID 38327746, 2024).
esophageal cancer (1 paper, 2022). A primary or metastatic malignant neoplasm involving the esophagus. "Active β-catenin, p-AKT, and p-GSK3β levels were restored in MAP3K9 overexpressing esophageal cancer cells after simultaneous stable expression of PCDH20." (PMID 36248995, 2022). "Transwell assay results demonstrated that PCDH20 inhibited migration and invasion in esophageal cancer cells." (PMID 36248995, 2022). "Taken together, these results demonstrated that the PCDH20 inhibited migration of esophageal cancer cells by downregulation of MAP3K9 expression, which antagonized Wnt/β-catenin signaling pathway." (PMID 36248995, 2022). "We found that PCDH20 was widely expressed in a variety of normal cells but frequently silenced in esophageal carcinoma cell due to promoter methylation." (PMID 36248995, 2022). "We found that PCDH20 expression was dramatically attenuated in esophageal cancer tissues and cells, maybe due to promotor methylation, and ectopic PCDH20 expression suppressed ESCC malignant biological phenotypes." (PMID 36248995, 2022). "PCDH20, as an anti-tumor gene in esophageal cancer cells, had a significant effect on the migration and invasion of ESCC cells, may mediated by inhibition of the MAP3K9/AKT/β-catenin pathway." (PMID 36248995, 2022). "Because PCDH20 had a significant inhibitory effect on the proliferation of esophageal carcinoma cells, we assessed effects on the apoptosis and cell cycle by utilizing flow cytometry, PCDH20 overexpression resulted in G1 phase cellular accumulation and increased esophageal cancer cells apoptosis." (PMID 36248995, 2022). "Taken together, silenced expression of PCDH20 may be related to promotor methylation in esophageal carcinoma cells." (PMID 36248995, 2022). "Furthermore, we transfected MAP3K9 into esophageal cancer cell lines that stably expressed PCDH20." (PMID 36248995, 2022). "MSP detected higher PCDH20 methylation in primary esophageal carcinoma tissues but no methylation in normal esophageal tissue samples (see at the end of manuscript)." (PMID 36248995, 2022).
hypopharyngeal cancer (1 paper, 2023). Carcinoma, predominantly squamous cell, arising from the epithelial cells of the hypopharynx. "In addition, we reviewed the literature and obtained several biomarkers that may be associated with the prognosis of hypopharyngeal cancer, such as PD-L1, SSR1, S100A4, PCDH20, and α2δ1." (PMID 36941989, 2023).
Insulin resistance (1 paper, 2019). Increased resistance towards insulin, that is, diminished effectiveness of insulin in reducing blood glucose levels. "Cadherin 3, type 1, P-cadherin (CDH3), CDH2, PCDH20, and CDH23 are novel biomarkers for the development of insulin resistance." (PMID 30678306, 2019).
Lassa fever (1 paper, 2021). A viral hemorrhagic fever that is caused by the Lassa virus, which is transmitted by contact with infected rodents; it is characterized by fever, headache, malaise, myalgia, and hearing loss. "Genes involved in extracellular matrix and cell-adhesion were also modulated, particularly during fatal Lassa fever (NID1, TIMP3, ITGA11, TGM2, MMP8/9, OLFM4, PCDH20, and CADM3), as well as some others involved in coagulation (SERPIN, TFPI2) and apoptosis (CLU, BCL2L14)." (PMID 33398113, 2021).
portal hypertension (1 paper, 2017). Increased blood pressure in the portal venous system. "Low PCDH20 expression was found to correlate with portal hypertension (P = 0.041), poor tumor differentiation (P = 0.016), advanced Okuda stage (P = 0.003), and Cancer of the Liver Italian Program (CLIP) score (P < 0.001)." (PMID 27935871, 2017). "Reduced protocadherin 20 protein expression correlated with portal hypertension, poor tumor differentiation, advanced Okuda stage, and Cancer of the Liver Italian Program score (all P < 0.05)." (PMID 27935871, 2017). "Decreased PCDH20 expression correlated with portal hypertension, poor tumor differentiation, advanced Okuda stage, and CLIP score, with patients with lower PCDH20 expression having a higher risk of mortality." (PMID 27935871, 2017).
steatosis (1 paper, 2021). Increased lipid within the cytoplasm of cells. "Eventually, we determined 10 hub genes (Down-regulated genes: MYC, TGFB3, ADAMTS1, THBS1, RASD1, PCDH20; Up-regulated genes: MAMDC4, CYP7A1, GINS2, and PDLIM3) related to NAS and steatosis." (PMID 34777484, 2021).
type 2 diabetes (1 paper, 2018). "Nine genes not previously reported to be associated with type 2 diabetes were significantly dysregulated in our organ donor and PPP cohorts (ANKRD23/39, ASCL2, HHATL, NSG1, PCDH20, SCTR, CD44, FAM102B and FBXO32)." (PMID 29185012, 2018).
Usher syndrome (1 paper, 2015). A syndromic diseae characterized by the association of sensorineural deafness (usually congenital) with retinitis pigmentosa and progressive vision loss. "PCDH20 belongs to the cadherin superfamily, whose members have multiple roles in cellular adhesion and have been previously implicated in murine hearing loss as well as in the human Usher syndrome." (PMID 26188009, 2015).
uveal melanoma (1 paper, 2024). A melanoma derived from melanocytes of the uveal tract. "For example, MAT1, a CNV-associated lncRNA, drives uveal melanoma by inhibiting the interaction between the MLL protein complex and the tumor suppressor PCDH20 promoter." (PMID 39350250, 2024).